CD4 (CD4 molecule)
Diseases named in the same sentence as CD4 in open-access papers (continued):
Sharing a sentence is not in itself a finding about the gene and the disease.
melanoma (continued). "In this study, we show that the blood TCR repertoires were variably restricted in CD4+ and extensively restricted in CD8+ T cells of patients with advanced melanoma, and contained clones in both T-cell fractions prior to the start of immunotherapy." (PMID 31275310, 2019). "Then, we next evaluated the cytotoxicity of splenic CD4+ and CD8+ T cells against B16F10 melanoma cells in vitro after cryo-thermal therapy with Siglec-F mAb by CCK-8." (PMID 31519961, 2019). "Before immunotherapy, TCR repertoires of both CD4+ and CD8+ T cells in melanoma patients were significantly more restricted compared to those from healthy controls." (PMID 31275310, 2019). "Bone marrow-derived primary MSCs or murine 10 T1/2 MSCs were tumor-conditioned (TC-MSCs) and co-cultured with B16 melanoma antigen-specific DCs and MACS purified CD4+ and CD8+ T cells." (PMID 31547863, 2019). "In a BRAFV600E/PTEN-driven murine model of melanoma, PLX4720 administration increased the expression of CD40 ligand and interferonγ (IFNγ) in intra-tumoral CD4 cells." (PMID 31762942, 2019). "To address this issue, we performed a detailed analysis of T-cell repertoires in patients with advanced melanoma using CDR3 size spectratyping and sequencing of TCR rearrangements in combination with CD4/CD8 T-cell separation." (PMID 31275310, 2019). "Composite images were analyzed using inForm® software to define cells as either melanoma (SOX10+) or T cells subsets (CD3+CD4+, CD3+CD8+, CD3+CD4+FoxP3+, CD3+ CD4−CD8−)." (PMID 30042403, 2018). "To investigate the effect of anti-CD4 mAb treatment on the TCR repertoire, we adopted the B16F10 mouse melanoma model." (PMID 30733724, 2018). "Assessment of tissue sections from tumor samples in the neoadjuvant melanoma ICB cohort demonstrated co-localization of the B cells in TLS with CD8 and CD4 T-cells and CD21 follicular dendritic cells." (PMID 30400822, 2018). "Preclinical studies investigating the role of CD4 T cell responses in MHC class II-positive tumors were performed in mouse models using the B16 melanoma cell line raising the question whether CD4 T cell responses are similarly regulated in other melanoma models and tumor types." (PMID 29032503, 2018). "DC vaccination successfully increased the frequency of functional melanoma-specific CD8 and CD4 T cells, and approximately 7–10% of tumour-specific CD8 cells were CTLA-4 positive while 20–28% were PD-1 positive." (PMID 29996914, 2018). "Comparison of the patient’s pre-hepatitis proportions of CD4+ T cells, CD8+ T cells, NK cells and B cells with melanoma patients and healthy controls indicated that they were within the normal range." (PMID 29289977, 2018). "As CD4+ TNaive cells were found reduced in young melanoma patients, we next determined if CD31+ thymic emigrant CD4+ TNaive cells or post-thymically expanded CD31− central CD4+ TNaive cells were decreased in young melanoma patients." (PMID 29546435, 2018). "An increase in circulating CD4+, CD8+ T cells and ALC, 2 to 8 weeks after treatment initiation with ipilimumab, was reported in melanoma patients with better clinical outcomes." (PMID 30546008, 2018). "The UltiMapper I/O T-Reg panel included the markers CD4, CD25, and FoxP3, as well as a tumor markers pan-cytokeratin (CK) for carcinomas and Sox10 for melanomas." (PMID 30400822, 2018). "On the aspect of CD molecular expression, increased CD4 and CD86 were detected on the melanoma models treated with Tα1 and Tα1-Fc." (PMID 30120362, 2018). "The effectiveness of immunotherapies against neoantigens has been convincingly demonstrated by induction of therapeutic CD4 and CD8 T cell responses in mouse models of melanoma, sarcoma, and colon cancer." (PMID 29032503, 2018). "Animals were implanted for 14 days with B16 melanoma cells, after receiving 3 doses of anti-PD-L1 the CD8/CD4 T cell ratio increases." (PMID 30400822, 2018).
melanoma (continued). "To this end, we isolated CD4+ T cells from TRP-1 mice, which express a MHC Class II-restricted, transgenic TCR specific for the tyrosinase-related protein 1 antigen present in melanoma." (PMID 30687308, 2018). "In another study, Wang and colleagues observed an upregulation of Ki67, ICOS, and GATA3 in blood CD4+ and CD8+ T cells of anti-CTLA-4 antibody-treated melanoma patients." (PMID 29494517, 2018). "We observed trends for increased proportions of CD4+ TCM and TEM cells in young melanoma patients versus age-matched controls, whereas proportions of CD4 TTD cells were similar in young patients and controls." (PMID 29546435, 2018). "To investigate the changes in the TCR repertoire induced by the anti-CD4 mAb treatment, we performed unbiased high-throughput TCR sequencing in a B16F10 mouse subcutaneous melanoma model." (PMID 30733724, 2018). "For example, it has been demonstrated that an increased frequency of blood-circulating ICOS+ CD4+ T cells, sustained over a period of 12 weeks of anti-CTLA-4 therapy, correlates with favorable clinical outcome in melanoma patients." (PMID 29494517, 2018). "In summary, Tα1-Fc inhibited the tumor growth on melanoma with an increased expression of IFN-γ, IL-2, and CD86 and of tumor-infiltrating CD4+ T and CD8+ T cells." (PMID 30120362, 2018). "Patients with advanced melanoma treated with pembrolizumab showed increased Ki-67 expression not only on CD8+ cells, but also CD4+ cell populations, lending in vivo support to these in vitro findings." (PMID 30285852, 2018). "To address this question, we flow-sorted murine TRP-1 CD4+ T cells, which express a transgenic TCR specific for tyrosinase on melanoma, via CD26 expression." (PMID 29213079, 2017). "Naïve and memory CD4+ T-cell stimulation.Th17 polarization.DC-10, skin CD141+CD14+ DCs and CD1c+CD14+ DCs in melanoma patients promote tolerance." (PMID 29250057, 2017). "In this study, we investigate the ability of ACT using CD4+ T helper 1 (Th1) cells and CD8+ cytotoxic T lymphocytes (CTLs) to reject the growth of established B16-ovalbumin (OVA) melanoma." (PMID 29114389, 2017). "We conclude that the induction of CD4+CD25hiFoxP3+ T cells and the expression of IDO and galectin-3 by melanoma cells are undesirable for a good expansion of tumor-reactive T cells in a MLTC." (PMID 28401257, 2017). "To summarise, this study demonstrated a fascinating antitumour response mediated by the joint action of antigen-specific CD4 Th1-like cells and CD8 CTLs in a mouse model of melanoma." (PMID 29114389, 2017). "Interestingly, IL-9 was recently shown to promote the survival and function of human melanoma-infiltrating CD4+CD8+ double-positive T cells, lending further support to the hypothesis that IL-9 may amplify anti-tumor immune responses by promoting T cell fitness in human melanoma." (PMID 27832300, 2017). "Our study also looked at cell-mediated immune activation and recognition of GA-DM-treated melanoma in vitro by using whole HSA protein or HSA64 76K peptide as a model for the study of Ag processing and presentation to specific CD4+ T cells." (PMID 29399381, 2017). "Because melanoma can expresses TRP-1, a melanocyte differentiation antigen expressed in the skin that is targeted by our TRP-1 specific CD4+ T cells, autoimmunity can ensue." (PMID 26981246, 2016). "CD4+ Trp-1 transgenic T cells and CD8+ Pmel-1 transgenic T cells can recognize tyrosinase-related protein 1 and gp-100, respectively, in B16 melanoma cells and have been used extensively in an adoptive cell transfer setting." (PMID 28123897, 2016). "We compared those exhausted T cell phenotype on CD4+ or CD8+ T cells between naive and melanoma-bearing mice." (PMID 27447564, 2016). "Similar to our results, the presence of CD4+ and CD4−CD8− human T cells that recognize melanoma antigens in an HLA class I-restricted manner was also found in humans." (PMID 26824989, 2016).
melanoma (continued). "While studies of anti-GITR in flank melanoma models have demonstrated CD8+ mechanistic dominance, more recent studies in flank tumor have emphasized the importance of CD4+ helper-T cells in coordinating a CD8+ anti-tumor response." (PMID 27190629, 2016). "Local low-dose CpG administration resulted in lower CD4/CD8 ratios, Th1 skewing, increased frequencies of melanoma-specific CD8+ T cells and possible recruitment of effector NK cells, irrespective of GM co-administration." (PMID 26935057, 2016). "In this study we demonstrate the efficient induction of high frequency and avidity melanoma antigen specific CD8 and CD4 responses from SCIB1 DNA vaccine." (PMID 27825115, 2016). "Collectively, our data suggest that concomitant triggering of CD137 and blocking of PD-1 signalling within irradiated melanomas enhance the intratumoral presence of both CD4+ and CD8+ T cells, which are in part required for melanoma Control." (PMID 27160390, 2016). "CTLA-4 blockade was shown to potentiate the production of TAA-specific antibodies as well as a CD4+ and CD8+ antigen-specific T cell response in patients with melanoma, ovarian and prostate cancer." (PMID 26788324, 2016). "To test this possibility, we depleted CD4+ and/or CD8+ T cells in melanoma-bearing mice just before initiating radio-immunotherapy." (PMID 27160390, 2016). "Th1 (CD4+ CXCR3+) and Th1-free T helper cells (CD4+ CXCR3-) were further enriched from healthy donors and were activated with PHA or anti-CD3 antibody in the absence or presence of melanoma-derived PAEP." (PMID 25785839, 2015). "Upon the enrichment of CD3+, CD4+ and CD8+ T cells from human peripheral blood mononuclear cells, each subset was then mixed with either melanoma-derived PAEP protein or PAEP-poor supernatant of gene-silenced tumor cells." (PMID 25785839, 2015). "Reduced frequencies of CD4+IFNγ+ T cells (Th1) and CD8+IFNγ+ T cells (Tc1) were found in melanoma patients at pre-vaccination as compared to healthy donors (p = 0.0005 and p = 0.001, respectively)." (PMID 26176858, 2015). "Thus, the correlation between high expression of these receptors and the low inhibition of proliferation induced by melanoma cells might be related to a different intracellular pathway activated by ADO in naïve CD4+ T cells and effector CD8+ T cells compared to the other subsets." (PMID 26329660, 2015). "To test the possibility that melanoma cell lines inhibited T cell proliferation through ADO production, we evaluated the proliferation of CD4+ and CD8+ T cells activated by anti-CD3/anti-CD28 beads in the presence or absence of primary melanoma cells." (PMID 26329660, 2015). "The inhibitory effects exerted by melanoma cells were tested on CD4+CD27+CD45RA+ naïve T cells, CD4+CD27+CD45RA− central memory T cells and CD4+CD27−CD45RA− effector memory T cells." (PMID 26329660, 2015). "Adoptive transfer of melanoma specific CD4+ T cells together with OX40 and cyclophosphamide eliminated even more advanced melanomas." (PMID 24855562, 2014). "We also conducted a flow cytometric analysis of systemic CD4+CD25+FOXP3+ T regulatory cells (Tregs) and histological analysis of melanoma tumors." (PMID 25428727, 2014). "CD4+ and CD8+ T cells from the healthy donors (stimulated with CMV pp65 or autologous LCL) and melanoma patient A02 (stimulated with the autologous melanoma cell line) cloned at comparable efficiencies (26-47% of all wells grew)." (PMID 25368986, 2014). "In a TCR-transgenic B16 melanoma model, MHCIIPOS melanoma cells are directly killed by cytotoxic CD4+ T cells in a perforin/granzyme B-dependent manner." (PMID 24782871, 2014). "CD4+ and CD8+ clones were stimulated with autologous or allogeneic melanoma cells, LCL or LCL loaded (or untreated) with CMV pp65 protein, as appropriate, and then culture supernatants were analysed for IFN-ã by ELISA." (PMID 25368986, 2014).
melanoma (continued). "Clonal expansion was successful for an average of 30% (CD4+) and 48% (CD8+) of effector T cells that were sorted from PBMC in response to autologous melanoma cells, LCL or a CMV protein." (PMID 25368986, 2014). "Recent work by Godefroy and colleagues showed that MMP-2 in melanoma degrades type I IFN receptor, effectively preventing IL-12p35 production, and skews CD4 T cells towards a Th2 phenotype." (PMID 25491880, 2014). "In many human cancers such as cervical, ovarian, melanoma, lymphoma, gastrointestinal, and head and neck cancer, level of tumor infiltrating CD8 versus CD4+Foxp3+ Treg cells provides strong prognostic factor." (PMID 23533812, 2013). "Conjugation of the anti-DEC-205 monoclonal antibody to the melanoma antigen tyrosinase-related protein TRP-2, induced CD4+ and CD8+ T-cell responses which protected mice against B16 tumor cell growth and slowed growth of established B16 tumors." (PMID 24228179, 2013). "Both CD4+ and CD8+ HAdV-5-specific T cell responses were examined in vitro, with cells from both 8 healthy donors (HD) and 2 melanoma patients." (PMID 24829755, 2013). "In phase I trials, gp100 peptides, a melanocyte lineage-specific protein expressed in most melanomas, elicited strong anti-melanoma CD8+ cytotoxic lymphocytes (CTLs) (in 14% of patients) and CD4+ helper T cell effects (in 79% of patients)." (PMID 23402570, 2013). "This likely contributes to the inhibition of the anti-tumor effects of adoptively transferred CD4+ and CD8+ T cells in this melanoma model." (PMID 24151492, 2013). "In order to formally characterize some of the recognized class II peptides, we derived CD4 T cells clones specific for the epitopes located within the different regions of MELOE-1 (from 3 healthy donors, and from one melanoma patient)." (PMID 23284752, 2012). "It is worth noting that some solid tumors, melanoma, for instance, can be induced to express MHC-II upon encountering IFNγ and thus become direct targets of CD4+ effector T cells." (PMID 22400040, 2012). "We confirmed these results in a panel of melanoma patients, and documented that MELOE-1 specific CD4 T cells, were mainly Th1 cells, presumably favourable to the amplification of CD8 specific T cells." (PMID 23284752, 2012). "In this study we found that adoptive transfer of antigen-specific T cells (both CD4 and CD8) also significantly promoted survival of mice with CD200-positive melanoma tumors over CD200-negative tumors." (PMID 22319630, 2012). "In conclusion, vaccination with MELOE-1 whole polypeptide should induce specific Th1 CD4 responses in a majority of melanoma patients, stimulating the amplification of CD8 effector cells, reactive against melanoma cells." (PMID 23284752, 2012). "The therapeutic activity of Surek was strictly dependent on CD4+ and CD8+ T cells, and cured mice developed a long-term memory response against a second challenge even with GD2-negative B16 melanoma cells." (PMID 23134699, 2012). "CD4+ Tregs that are specific for the LAGE1 and ARTC1 tumor antigens have been identified in melanoma, and EBNA1 P561-573 and P607-619 peptide-specific CD4+ Tregs have been identified in PBMCs from healthy donors." (PMID 22051182, 2011). "We have previously demonstrated that temporary depletion of CD4 T cells in mice with progressive B16 melanoma, followed by surgical tumor excision, induces protective memory CD8 T cell responses to melanoma/melanocyte antigens." (PMID 22046294, 2011). "B16 melanoma produces TGFβ and both pmel CD8 and OTII CD4 express TCR that should be engaged within B16 and B16-OVA respectively." (PMID 22112546, 2011). "We have tested CD8 and CD4 TIL, which were isolated from melanoma and carcinomatous ascites of the ovary, colon, and pancreas." (PMID 24212939, 2011). "The observation that the highest ranked immune genes in these comparisons, CD4 and CD8, were upregulated in primary melanoma and metastasis compared to normal melanocytes signified early and enduring T-cell infiltration." (PMID 21453479, 2011).
melanoma (continued). "Herein we explore the requirement of CD4 T cell help in priming and maintaining this protective CD8 T cell response to melanoma." (PMID 22046294, 2011). "We confirmed that Foxp3-positive CD4 T cells are enriched among tumor-infiltrating lymphocytes (TIL) and splenocytes (SPL) in B16 murine melanoma-bearing C57BL/6 Foxp3EGFP mice." (PMID 22112546, 2011). "In conclusion, we show that CD4+CD25+ Treg appear to have little effect on the number, phenotype and function of TIDC in B16 melanoma, suggesting that the delayed tumor growth observed in Treg-depleted mice is unlikely to be due to improved DC function." (PMID 21390236, 2011). "In the next step we analyzed peripheral blood cells from HLA-DRB1*03+ melanoma patients and HLA-DRB1*0301+ normal donors for the presence of TRP-164–78- and TRP-1284–298-specific CD4+ T cells." (PMID 21152437, 2010). "Current studies suggest that malignant melanomas can constitutively express Human Leukocyte Antigen (HLA) class I and II molecules which are essential for the stimulation of CD8+ and CD4+ T cells." (PMID 20016802, 2009). "The ability of each of these peptides to generate effective CD4+ and CD8+ antitumor immune responses makes them attractive targets for treating melanoma." (PMID 20016802, 2009). "DAB/IL2 administration transiently decreased CD4+CD25-, CD4+CD25+, CD4+CD25HIFoxp3-, CD4+CD25HIFoxp3+, CD8+ T cells and, in certain patients, melanoma antigen-specific CD8+ T cells." (PMID 18334033, 2008). "Furthermore, presentation by DCs of Ags generated in apoptotic melanoma cells has the potential benefit that presentation via HLA class II may generate helper epitopes that support the development of specific CD4+ lymphocytes that might be important for antitumoral immunity." (PMID 17448240, 2007). "CD4 and CD8 staining also revealed the presence of a mild to moderate T cell infiltrate inside melanoma cell nests in the majority of cases; usually intratumoral CD4+ and CD8+ T cells were co-localized within the lesion (data not shown)." (PMID 17129373, 2006). "DTH is considered to be a classical CD4+ T cell response, but both CD4+ and CD8+ T cell subsets with anti melanoma reactivity were isolated from skin biopsies of DTH sites." (PMID 12085200, 2002). "Epitope-specific CD4+ T cells from normal DR4+ donors could be induced, however, after in vitro stimulation with autologous dendritic cell pulsed with antigens (peptides or antigen-positive melanoma lysates) or infected with recombinant vaccinia virus encoding the relevant antigen." (PMID 11742496, 2001). "Bcl6fl/fl CD4-cre mice, which lack BCL6 in both CD4 and CD8 T cells, starting at the double-positive stage of T-cell development, showed inhibited growth of MC38, LLC1 (Lewis lung carcinoma), and B16F10 (melanoma) tumors compared with Bcl6fl/fl control mice." (PMID 41145211, 2026). "Furthermore, the optimized LNP potently activated dendritic cells, expanded antigen-specific CD4+ T cell populations, and significantly inhibited tumor growth in a B16-ovalbumin (OVA) melanoma model." (PMID 41541271, 2026). "Our data support prior studies showing increased TIL at 1–2 weeks after BRAF/MEKi therapy for advanced melanoma and extend those findings by showing that this increase in TIL persists in most patients through the first month, including both CD8 and CD4 T cells." (PMID 41514118, 2026). "In hAAT-TG mice, melanoma growth was markedly inhibited compared with wild-type controls, and the inhibitory effect required CD8+ T cells and was enhanced by CD4+ T-cell depletion, demonstrating that AAT promotes cytotoxic T-cell activity while attenuating regulatory T-cell suppression." (PMID 41594664, 2026). "Notably, genetic knockout of FTO in melanoma cells resulted in a marked increase in CD4 + tumor-infiltrating lymphocyte (TIL) numbers and IFN-γ production in B16F10 melanoma following anti-PD-1 blockade." (PMID 39987091, 2025).